CCL2 (C-C motif chemokine ligand 2)
Diseases named in the same sentence as CCL2 in open-access papers (continued):
Sharing a sentence is not in itself a finding about the gene and the disease.
endometrial cancer (7 papers, 2018 to 2025). Primary or metastatic malignant neoplasm involving the endometrium (mucous membrane that lines the endometrial cavity). "A further multiple-SNP analysis in our study also showed that the T-A-A haplotypes for the CCL2 rs4586-CCL5 rs2107538-CCL5 rs2280789 polymorphisms had correlated with an increased risk of endometrial cancer." (PMID 38001676, 2023). "Considering the women with endometrial cancer, C and T alleles in CCL2 polymorphism demonstrated prevalence rates of 12.3% (32/260) and 87.7% (228/260), respectively." (PMID 38001676, 2023). "In endometrial cancer, the T allele in CCL2 rs4586 may also be involved in the elevated CCL2 production previously established for this type of malignancy." (PMID 38001676, 2023). "Despite the dominant role of the CCL2-CCR2 axis in TAM recruitment, CCL2 deletion resulted in an approximately 60% TAM reduction in mouse models of endometrial cancer 14, suggesting the involvement of additional chemoattractant signals to attract TAMs." (PMID 40756366, 2025). "CCL2 rs4586, CCL5 rs2107538 and rs2280789, as well as CXCR2 rs1126580, seem to be significantly associated with an increased risk of endometrial cancer in the population of Polish women." (PMID 38001676, 2023). "The A-A haplotypes for the CCL5 polymorphisms and T-A-A haplotypes for the CCL2 and CCL5 SNPs were associated with about a twofold risk of endometrial cancer (p ≤ 0.050)." (PMID 38001676, 2023). "In this case-control study, we aimed to identify the possible associations between selected single nucleotide polymorphisms (SNPs), localized in the CCL2, CCL5, CXCL8, and CXCR2 genes, and the onset and progression of endometrial cancer." (PMID 38001676, 2023). "The reported case-control study of genetic associations was designed to establish the role of selected single nucleotide polymorphisms (SNPs) of the CCL2, CCL5, CXCL8, and CXCR2 genes in the onset and progression of endometrial cancer." (PMID 38001676, 2023). "Significant relationships with endometrial cancer were demonstrated, both for CCL2, CCL5, and CXCL8 chemokines and for the chemokine receptor CXCR2." (PMID 38001676, 2023). "Among the patients with endometrial cancer, TT, TC, and CC genotypes in CCL2 903 T>C SNP, were determined in 86.2% (112/130), 3.1% (4/130), and 10.8% (14/130) of the patients, respectively." (PMID 38001676, 2023). "In conclusion, CCL2 rs4586, CCL5 rs2107538 and rs2280789, and CXCR2 rs1126580 demonstrated significant associations with an increased risk of endometrial cancer." (PMID 38001676, 2023). "Genetic studies confirm the association of the single nucleotide polymorphisms (SNPs) −2518 G>A (rs1024611) of the CCL2 gene and 190 G>A (rs1799864) of the CCR2 gene with the occurrence of endometrial cancer." (PMID 38001676, 2023). "Tamoxifen decreased CCL2 secretion and mRNA and protein levels in the human endometrial cancer cell line EFE-184." (PMID 36403055, 2022). "In this review, we summarize the evidence for the involvement and potential therapeutic target of CCL2 in gynecological malignancies, focusing on breast, ovarian, cervical, and endometrial cancers." (PMID 36403055, 2022). "Interleukin-17 induced CCL2 mRNA levels in human endometrial cancer cell line HEC-1-B in particular by activating IκBα and extracellular signal-regulated kinase 1/2." (PMID 36403055, 2022). "In endometrial cancers, established in mice by loss of liver kinase B1 (LKB1) tumor suppressor gene (Lkb1−/−), the CCL2 level is markedly increased in cancer cells." (PMID 30483271, 2018). "A multiple-SNP analysis determined A-A haplotypes, for both CCL5 polymorphisms and T-A-A haplotypes in the range of CCL2 and CCL5 SNPs to be associated with an approximately twice higher risk of endometrial cancer (OR 1.84 95% CI 1.21–2.81, and OR 1.71 95% CI 1.10–2.65, respectively, p ≤ 0.050)." (PMID 38001676, 2023).
endometrial cancer (continued). "Furthermore, numerous studies have shown that CCL2 regulates endometrial cancer progression through the recruitment of macrophages." (PMID 36403055, 2022). "Moreover, ATF4 regulated macrophage infiltration by mediating the expression of CCL2, which ultimately led to the growth of endometrial cancer." (PMID 36403055, 2022). "Since high ATF4 expression correlates with high macrophage density in human endometrial cancer, up-regulation of this transcription factor in cancer cells might be another mechanism behind CCL2-induced TAM accumulation in endometrial cancer." (PMID 30483271, 2018). "Furthermore, CCL2 inactivation also delayed the growth of endometrial cancer and improved survival." (PMID 36403055, 2022). "In endometrial cancer, STK11 inactivation enhances MCP-1/CCL2 expression, which increases immune cell recruitment." (PMID 41051525, 2025). "On the other hand, a recent study showed that AN3CA and KLE endometrial cancer cells produce CCL2 via activating transcription factor 4 (ATF4), and that anti-CCL2 neutralizing antibody treatment suppresses macrophage infiltrations in subcutaneous tumors developed by AN3CA or KLE cells." (PMID 30483271, 2018). "Considering endometrial cancer, a significant relationship was noted between its incidence and pathogenesis on the one hand and CCL2, CCL5, and CXCL8 chemokines, and their selected receptors, including CCR2 (the receptor for CCL2) and CXCR2 (the receptor for CXCL8) on the other." (PMID 38001676, 2023). "There is still a lack of understanding of CCL2’s role in endometrial cancer." (PMID 36403055, 2022).
endometritis (7 papers, 2020 to 2025). An acute or chronic, usually bacterial infectious process affecting the endometrium. "Gene expression levels were considerably higher in endometritis-affected buffaloes than in resistant ones for the genes A2M, TLR2, IRAK3, CCl2, FCAMR, iNOS, ADAMTS20, KCNT2, MAP3K4, MAPK14, FKBP5, and EPHA4." (PMID 38459095, 2024).
Erythema (7 papers, 2012 to 2026). Redness of the skin, caused by hyperemia of the capillaries in the lower layers of the skin. "Erythema in particular was drastically diminished upon CCL2 KD, and this effect was independent of tumor size." (PMID 34824220, 2021). "Of note, SUM149, an IBC line, which does not express CCL2 at the RNA and protein level, showed a much less aggressive IBC phenotype, lacking erythema or dermal lymphatic invasion and with significantly less inflammatory infiltrate as compared to A3250." (PMID 34824220, 2021).
focal segmental glomerulosclerosis (7 papers, 2017 to 2025). A renal disorder characterized by sclerotic lesions in the glomeruli. "Accordingly, Vianna and co-workers previously found higher urinary levels of MCP-1/CCL2 in patients with CKD due to focal segmental glomerulosclerosis than in cases of congenital uropathies." (PMID 30514826, 2019).
Hyperammonemia (7 papers, 2022 to 2026). An increased concentration of ammonia in the blood. "We show now that HA-EVs also increases CCL2 content in cerebellum of control rats and this is associated with microglia activation, thus reproducing the effects found in hyperammonemia." (PMID 35911759, 2022). "Hyperammonemia also increased the CCL2 content in the hippocampus, which was also reversed by blocking S1PR2 or IL-1R." (PMID 38139078, 2023). "To assess if this hypothesis is correct, we analyzed the effects of hyperammonemia and of blocking S1PR2 or IL-1R on the phosphorylation of Src and CCL2 contents." (PMID 38139078, 2023). "EV from control monocytes treated with TNFα (C-M-EV+TNFα) also induced some of the effects induced by hyperammonemia on these pathways, except for the increase of TNFα in microglia and in the whole hippocampus and the increases in TNFR1, IL-1 receptor, and CCL2." (PMID 41601700, 2026). "However, the EV from control monocytes treated with forskolin (C-M-EV+Forsk) induced most of the changes in these pathways induced by hyperammonemia, except for the changes in membrane expression of TNFR1, S1PR2, and GluA1 and the increase in IL-1 receptor and CCL2." (PMID 41601700, 2026).
keloid (7 papers, 2012 to 2025). An irregularly shaped, elevated mark on the skin caused by deposits of excessive amounts of collagen during wound healing. "TGF-β works in tandem with IL17A to stimulate IL-6 and CCL2 production in fibroblasts, which are macrophage chemokines and offer a way for macrophages to be recruited to the keloid microenvironment." (PMID 37895153, 2023). "CCL2 and CCR2 expression is reportedly enhanced in keloid tissue, increasing fibroblast proliferation." (PMID 37524866, 2023). "In this study, CCL2 and CCL3 expression was significantly elevated in the perigraft and intragraft areas, contributing to keloid-lesion integrity and augmenting fibrosis." (PMID 37524866, 2023). "By sustaining the expression of CCL2, CSF1, and IL-6, fibroblasts give signals for the chemotaxis, residency, and activation of macrophages in keloids." (PMID 37895153, 2023). "We also examined secretion of a previously established wound healing mediator panel (CCL2, IL-6, CXCL8, VEGF, HGF and CCL27), which showed reduced HGF secretion in the reconstructed keloid model compared to the normal skin model." (PMID 31187196, 2019).
malnutrition (7 papers, 2013 to 2025). Inadequate nutrition resulting from poor diet, malabsorption, or abnormal nutrient distribution. "As with CCL2, significant changes in muscle composition are observed in patients with cancer and malnutrition, suggesting an important relation between muscle homeostasis, inflammation and inflammasome components." (PMID 35158762, 2022). "Additionally, a clear dysregulation of key components of the inflammasome machinery (especially p27, CCL2 and ASC) in these patients has been observed, which may be closely related to the diagnosis of malnutrition and its clinical consequences." (PMID 35158762, 2022). "A molecular fingerprint based on gene-expression of certain inflammasome factors (p27/CCL2/ASC) in PBMCs accurately differentiated patients with and without malnutrition." (PMID 35158762, 2022).
membranous nephropathy (7 papers, 2014 to 2025). "The expression of CCL2 is typically observed in immune cells, such as macrophages, in membranous nephropathy." (PMID 40723524, 2025). "CCL2 was found to be exclusively highly expressed in IgAN patients compared with healthy controls, minimal change disease, and membrane nephropathy patients in a validation study." (PMID 36766548, 2023).
memory impairment (7 papers, 2009 to 2025). "To establish a spatial learning and memory impairment model, we infused CCL2 (5 ng) into the bilateral hippocampus of rats and measured the spatial learning and memory deficits by the MWM test." (PMID 32185196, 2020). "To evaluate the protective role of naringin in CCL2-induced spatial learning and memory impairment, we performed the MWM test." (PMID 32103758, 2020). "Since Aβ oligomer levels directly correlate with memory impairment, it is likely that CCL2 accelerates the onset of memory impairment by enhancement of Aβ oligomerization in the brain." (PMID 19593388, 2009). "Consistent with previous reports, APP mice develop memory impairments by 8–9 months when compared to age-matched WT or CCL2 littermates (T4 and T5)." (PMID 19593388, 2009). "The data support the idea that CCL2 is a co-factor in Aβ-induced memory impairment for APP mice." (PMID 19593388, 2009). "APP and CCL2 mice have normal memory function at 2–3 months of age, whereas APP/CCL2 mice have already developed memory impairment." (PMID 19593388, 2009). "However, APP/CCL2 mice show more severe memory impairments as determined by errors and latencies at T4 and T5, when compared to APP, CCL2, or WT mice." (PMID 19593388, 2009).
microcephaly (7 papers, 2015 to 2023). A congenital or acquired developmental disorder in which the circumference of the head is smaller than normal for the person's age and sex. "Interestingly, the levels of chemokines associated with microcephaly in humans, including CCL2 and CXCL10, specifically increased in embryos harboring ZIKV in the embryo brains." (PMID 31212905, 2019). "The microcephaly group exhibited significantly decreased CCL2 and CXCL8 levels in serum, quantified by CBA assay." (PMID 37766239, 2023). "Corroborating these results, it has been shown that CCL2 levels were found to be increased in the amniotic fluid of ZIKV-positive women giving birth to babies with neonatal microcephaly, relative to uninfected control group." (PMID 31212905, 2019). "A polyfunctional immune activation associated with increased CCL2, CXCL10, IL-6, IL-8, VEGF, and G-CSF levels but decreased levels of IL-13 was also described in the amniotic fluid of ZIKV-positive pregnant women whose infants had microcephaly." (PMID 29768624, 2018). "In the ZIKV-exposed group without microcephaly, we identified a predominance of decreases in most parameters related to controls, except for MCP1 (CCL2) levels, that were significantly increased." (PMID 33875756, 2021). "When cases with and without microcephaly were compared IL-4 and TNF-β were significantly higher and MCP1 (CCL2) was significantly lower among microcephalic cases." (PMID 33875756, 2021).
Miscarriage (7 papers, 2014 to 2022). A pregnancy that ends at a stage in which the fetus is incapable of surviving on its own, defined as the spontaneous loss of a fetus before the 22th week of pregnancy. "However, in contrary to this observation, serum levels of CCL-2/macrophage inflammatory protein (MIP-1) were elevated in women with recurrent spontaneous abortion (RSA) after spontaneous abortion occurred, whereas other studies did not see any significant alteration." (PMID 30266090, 2018). "In conclusion, we have found plasma concentrations of the cytokines IL-1β, IL-6 and IL-10, and the chemokines, CXCL8, CCL2, CCL5, CCL7, CX3CL1 cannot predict subsequent miscarriage." (PMID 24699265, 2014).
myelofibrosis (7 papers, 2013 to 2024). A partial or complete replacement of the bone marrow stroma by fibrous tissue. "The -2518 A/G SNP of CCL2 has emerged as a potential susceptibility marker for MPN and myelofibrosis." (PMID 39850880, 2024). "Importantly, CCL2 levels exhibit only a moderate correlation with MCs infiltration in the bone marrow and instances of myelofibrosis." (PMID 39850880, 2024). "Additionally, polymorphisms in the CCL2 gene have been shown to influence the bone marrow microenvironment in MPN, with homozygosity for the CCL2 rs1024611 SNP linked to diminished survival in individuals with primary myelofibrosis." (PMID 39850880, 2024). "The relative frequency of iFibs was 2-fold higher in myelofibrosis mice than controls, and expression of chemokine genes was strongly enriched in the iFibs with significantly increased per cell expression of chemokines in MPL vs. control fibroblasts, including Kitl, Cxcl12, Ccl2, Cxcl1." (PMID 39383242, 2024).
overnutrition (7 papers, 2011 to 2024). An imbalanced nutritional status resulting from excessive intake of nutrients. "Overnutrition increases the levels of inflammatory molecules, such as TNF, IL-6, CCL2 and CCL3, in adipocytes, which activate resident macrophages, leading to the recruitment of more immune cells." (PMID 35112705, 2022).
prion disease (7 papers, 2012 to 2021). A transmissible disease that is caused by a protein that is able to induce abnormal folding of normal cellular proteins, leading to characteristic spongiform brain changes, which are associated with neuronal loss without an inflammatory response. "In an animal model of prion disease, mice deficient in CCL2/MCP-1 showed a delayed onset of inflammatory disease and an increase in survival time." (PMID 22339770, 2012). "The effect of deleting some genes, such as Ccl2 and IL-10, on prion disease have proven controversial by both shortening and extending survival times in mice depending on the study." (PMID 30650564, 2019). "Both CCL2 and CCR2 are upregulated in prion disease, as reported in the present work and previously, indicating a potential role for of this receptor-ligand interaction." (PMID 24648328, 2014). "In our model of prion disease, we found a significant increase in the levels of Ccl2 transcript in the absence of PD-1, a chemokine which is a well-known inductor of the recruitment of myeloid cells into the CNS." (PMID 30086399, 2018).
renal carcinoma (7 papers, 2011 to 2023). A carcinoma arising from the epithelium of the renal parenchyma or the renal pelvis. "Thus, the blockade of the CCL2/CCR2 signaling pathway to treat renal cancer is a promising direction and deserves further investigation." (PMID 27409666, 2016).
respiratory infections (7 papers, 2019 to 2025). "Dysregulated gut ecology has been found to be associated with increased mortality from respiratory infections, possibly due to dysregulated immune responses, increased CCL2 secretion, and reduced numbers of lung regulatory T cells." (PMID 38803488, 2024). "HCoV-OC43, a common human coronavirus, typically causes mild respiratory infections but can induce cytokine and chemokine responses in infected individuals, such as IL6, TNF-α, IL-8, CCL2 (MCP-1), and CCL5." (PMID 40872743, 2025).
rheumatic diseases (7 papers, 2010 to 2024). "Monocyte migration in response to CCL2 is an integral part of the pathophysiology seen in rheumatic diseases, pathologies that are known to also involve Wnt signaling." (PMID 38622714, 2024). "For example, IL-37, a member of the IL-1 family which is stimulated by SARS-CoV-2, has been shown to suppress IL-1β, IL-6, TNFα and CCL2 in rheumatic diseases by acting on mTOR and enhancing the AMPK activity, to maintain mitochondrial membrane potential and limit the toxic effects of ROS." (PMID 36389723, 2022).